GATAD2A (GATA zinc finger domain containing 2A)
Description:
Transcriptional repressor. Acts as a component of the histone deacetylase NuRD complex which participates in the remodeling of chromatin. Enhances MBD2-mediated repression. Efficient repression requires the presence of GATAD2B.
Synonyms: p66alpha
Tractability: PROTAC: UniProt records ubiquitination sites on it; ubiquitination databases record sites on it; its protein half-life has been measured.
Gene: Protein-coding gene on chromosome 19 (19,385,638 to 19,508,932, forward strand). Ensembl gene ENSG00000167491.
Subcellular location: Nucleus speckle; Nucleus; Chromosome
Subcellular location (Human Protein Atlas): Nucleoplasm
Pathways (Reactome):
Gene expression (Transcription): ERCC6 (CSB) and EHMT2 (G9a) positively regulate rRNA expression; RNA Polymerase I Transcription Initiation; Regulation of endogenous retroelements by KRAB-ZFP proteins; Regulation of endogenous retroelements by Piwi-interacting RNAs (piRNAs)
Chromatin organization: HDACs deacetylate histones; Interaction of NuRD complexes with transcription factors; NuRD complex assembly
Developmental Biology: Differentiation of naive CD4+ T cells to T helper 2 cells (Th2 cells); Transcriptional regulation of brown and beige adipocyte differentiation by EBF2
Disease: Potential therapeutics for SARS
Signal Transduction: Regulation of PTEN gene transcription
Gene Ontology:
Molecular function: protein binding; protein-macromolecule adaptor activity; DNA-binding transcription factor activity, RNA polymerase II-specific; sequence-specific DNA binding
Biological process: chromatin remodeling; negative regulation of DNA-templated transcription; negative regulation of transcription by RNA polymerase II; positive regulation of DNA-templated transcription; regulation of cell fate specification; regulation of stem cell differentiation; regulation of DNA-templated transcription
Cellular component: chromosome; nuclear speck; nucleoplasm; nucleus; NuRD complex
Genetic constraint (gnomAD): Loss-of-function variants: 12 observed, 65.94 expected, observed/expected ratio (o/e) 0.18, 90% interval 0.12 to 0.29. The upper end of that interval is the gene's LOEUF score, 0.29, which puts it in group 1 of 6, group 1 being the genes least tolerant of losing a copy. Missense variants: 710 observed, 858 expected, observed/expected ratio (o/e) 0.83, 90% interval 0.78 to 0.88. Synonymous variants: 390 observed, 375.2 expected, observed/expected ratio (o/e) 1.04, 90% interval 0.96 to 1.13.
Homologues: Orthologues: chimpanzee GATAD2A (99% identical), macaque GATAD2A (99% identical), dog GATAD2A (93% identical), pig GATAD2A (93% identical), guinea pig GATAD2A (90% identical), rat Gatad2a (89% identical), rabbit GATAD2A (89% identical), mouse Gatad2a (88% identical), tropical clawed frog gatad2a (62% identical), zebrafish gatad2ab (56% identical), Drosophila melanogaster simj (35% identical), Caenorhabditis elegans dcp-66 (21% identical). Paralogues in human: GATAD2B (40% identical).
Diseases named in the same sentence as GATAD2A in open-access papers:
GATAD2A is named in the same sentence as 28 diseases in open-access papers, as found by Europe PMC text mining. Sharing a sentence is not in itself a finding about the gene and the disease. The quoted sentences say what the papers report.
schizophrenia (13 papers, 2018 to 2024). A major psychotic disorder characterized by abnormalities in the perception or expression of reality. "We observe a genetic correlation of 0.14 (95% CI 0.09–0.19) and identify a shared locus at 19p13 (GATAD2A) associated with risks of breast cancer and schizophrenia." (PMID 32934226, 2020). "Interacting partners BCL11B and GATAD2A are also schizophrenia risk genes indicating that other genes interacting with or are regulated by SATB2 are making a contribution to schizophrenia and cognition." (PMID 30040823, 2018). "The results of several studies indicate that GATAD2A may be one of the causal genes in the pathogenesis of schizophrenia, potentially through dopamine receptor D2 and nerve growth factor (NGF) pathways." (PMID 32934226, 2020). "By integrating the results from different prediction approaches, they identified six top candidates that represent promising causal genes for schizophrenia (CNTN4, GATAD2A, GPM6A, MMP16, PSMA4, and TCF4), including the GPM6A gene." (PMID 35328011, 2022). "Genetic correlations between schizophrenia and cerebellar volume are observed in two loci that include MPHOSPH9 and GATAD2A as most significant signal in schizophrenia." (PMID 35842455, 2022). "Among the 41 prioritized causal genes, CNTN4, GATAD2A, GPM6A, MMP16, PSMA4, and TCF4 represent the most promising causal genes for schizophrenia." (PMID 29540662, 2018). "Notably, this list contains genes that have also been identified by other independent studies as being shared between disease pairs, such as the GATAD2A gene for breast cancer and schizophrenia." (PMID 39538313, 2024). "Of note, five (CNTN4, GATAD2A, GPM6A, MMP16, and TCF4) of the top six causal genes are involved in neurodevelopment, further supporting the neurodevelopmental hypothesis of schizophrenia." (PMID 29540662, 2018). "We found that GATAD2A and TCF4 were significantly upregulated in the hippocampus of schizophrenia cases compared with controls in GSE53987 dataset (P < 0.01)." (PMID 29540662, 2018).
breast carcinoma (6 papers, 2020 to 2025). "CARM1’s function in breast cancer is, at least partially, mediated through its methyltransferase activity targeting GATAD2A." (PMID 38676947, 2024). "Knockdown of CARM1 and GATAD2A significantly attenuates breast cancer cell growth both in vitro and in vivo." (PMID 38676947, 2024). "Both CARM1 and GATAD2A were found to be expressed higher in breast tumor than normal samples, and their high expression predict poor prognosis in breast cancer patients." (PMID 38676947, 2024). "Targeting CARM1-mediated GATAD2A/2B methylation with CARM1 specific inhibitors potently inhibit breast cancer cell growth in vitro and tumorigenesis in vivo." (PMID 38676947, 2024). "We demonstrated that CARM1-mediated GATAD2A methylation was important for the growth of breast cancer cells both in vitro and in vivo." (PMID 38676947, 2024). "The clinical relevance of CARM1-mediated GATAD2A methylation in cell cycle control is further illustrated in breast cancer, where higher expression of CARM1 and GATAD2A is observed compared to normal tissues." (PMID 38676947, 2024). "Taken together, our data suggested that CARM1-mediated GATAD2A methylation is involved in breast cancer cell growth and tumorigenesis." (PMID 38676947, 2024). "Next, we examined whether CARM1-madiated GATAD2A methylation is required for breast cancer cell growth and tumorigenesis." (PMID 38676947, 2024). "Our data thereby suggested that CARM1-mediated GATAD2A methylation might serve as a potential druggable target in breast cancer." (PMID 38676947, 2024). "Therefore, targeting CARM1 enzymatic activity or peptide mimics interfering CARM1-mediated GATAD2A/2B methylation will provide a new therapeutic avenue for treating breast cancer as well as other CARM1-dependent cancers." (PMID 38676947, 2024). "Consistent with this idea, our results show that GATAD2B, but not GATAD2A, can regulate CSCs function in breast cancer further implicating a specific role of GATAD2B in CSCs." (PMID 40136647, 2025). "Altogether, this data indicates that GATAD2B, but not GATAD2A, regulates cancer stem-like cell populations and cancer stem cell factors in breast cancer cells." (PMID 40136647, 2025). "The functional role of CARM1-mediated GATAD2A methylation in breast cancer cell growth prompted us to examine whether targeting CARM1-mediated GATAD2A methylation using CARM1 inhibitors, EZM2302 and TP-064, could inhibit breast cancer cell growth." (PMID 38676947, 2024).
papillary thyroid cancer (4 papers, 2019 to 2022). "For example, Hsa_circ_0058124 facilitated papillary thyroid cancer progression and invasiveness via the NOTCH3/GATAD2A axis." (PMID 36072578, 2022).
thyroid cancer (2 papers, 2019 to 2021). "A previous study reported the differential expression of GATAD2A in thyroid cancer and suggested its possible involvement in thyroid cancer progression." (PMID 31324198, 2019). "Circ_0058124 enhances the progression of thyroid cancer via the NOTCH3/GATAD2A signaling." (PMID 34290668, 2021).
breast tumor (1 paper, 2024). "Targeting CARM1 with EZM2302, a CARM1-specific inhibitor, significantly inhibits CARM1-mediated GATAD2A methylation, cell cycle gene transcription, cell cycle progression, and breast tumor growth." (PMID 38676947, 2024).
embryonal carcinoma (1 paper, 2022). A non-seminomatous malignant germ cell tumor characterized by the presence of large germ cells with abundant cytoplasm resembling epithelial cells, geographic necrosis, high mitotic activity, and pseudoglandular and pseudopapillary structures formation. "Several studies have shown potential interaction between SOX2 and MTA1/2/3, MBD2, GATAD2A/B, and HDAC1/2 in different cell lines, including embryonic stem cells, neural stem cells, and embryonal carcinoma cells." (PMID 35615634, 2022).
Infertility (1 paper, 2023). "Additionally, POLR2J3, MMP17, MED17, and GATAD2A are associated with various conditions ranging from infertility to neuroinflammation." (PMID 38681774, 2023).
Insulin resistance (1 paper, 2017). Increased resistance towards insulin, that is, diminished effectiveness of insulin in reducing blood glucose levels. "Five SNVs in genes AABR06087018.1, Pms2, Zfp866, Gatad2a and Daglb were found to be exclusively associated with insulin resistance." (PMID 28130354, 2017). "Although these two studies highlight some genes in common (such as the plausible candidates Lpl and Gatad2a), our study, of congenic strains on chromosomes 12 and 16, was carried out in linkage regions to adipocyte insulin resistance that we had defined previously." (PMID 28130354, 2017).
Obesity (1 paper, 2021). Accumulation of substantial excess body fat. "GATAD2A is involved in embryonic development and associates with obesity." (PMID 33472578, 2021).
sarcoma (1 paper, 2021). A usually aggressive malignant neoplasm of the soft tissue or bone. "In the 255 sarcomas of the TCGA PanCancer Atlas Studies, alterations were found for SLC25A39,GLT8D1 and GATAD2A in 0.78%, 1.57%, and 2.75% of cases, respectively." (PMID 33963205, 2021).
steatosis (1 paper, 2025). Increased lipid within the cytoplasm of cells. "In addition, GWAS fine mapping identified potential causal variants in GATAD2A, SUGP1, and MAU2, while TWAS fine mapping implicated SAMM50 as a driver of steatosis in normal-weight individuals, possibly through changes in gene expression." (PMID 40677695, 2025).
thyroid tumor (1 paper, 2019). A benign or malignant neoplasm affecting the thyroid gland. "We also validated the differential expression of GATAD2A in PTC by examining IHC staining data of thyroid tumor tissues and normal thyroid tissues from the Human Protein Atlas." (PMID 31324198, 2019). "All 4 thyroid tumor samples showed medium expression of GATAD2A, while all 3 normal samples showed high expression." (PMID 31324198, 2019).
tongue squamous cell carcinoma (1 paper, 2022). A squamous cell carcinoma that arises from the tongue. "In tongue squamous cell carcinoma, lncKRT16P6 acts as a trap for binding miR-3180 to promote the expression of GATA zinc finger domain containing 2A (GATAD2A), thus leading to tumorigenesis and metastasis." (PMID 36612282, 2022).
cancer (5 papers, 2018 to 2025). A tumor composed of atypical neoplastic, often pleomorphic cells that invade other tissues. "The functional role of CARM1-mediated GATAD2A methylation in cell cycle gene transcriptional activation and cell cycle progression prompted us to examine its role in cancer." (PMID 38676947, 2024). "GATAD2A can have either cancer suppressive or cancer promotive role depending on the context since it is a nucleosome remodeling and deacetylase (NuRD) complex subunit." (PMID 35681732, 2022).
tumor (5 papers, 2019 to 2024). "In consistent with what we observed in cultured cells, GATAD2A 7R/K mutant was less effective in rescuing the tumor growth defects caused by GATAD2A knockdown." (PMID 38676947, 2024). "rs2965183 is located in enhancer elements reported to interact with GATAD2A in normal and tumor breast cells." (PMID 32934226, 2020). "For example, hsa_circ_0058124 enhances PTC tumor invasion via the NOTCH3/GATAD2A pathway." (PMID 39051062, 2024). "The involvement of CARM1-mediated GATAD2A methylation in tumor growth was also tested." (PMID 38676947, 2024). "Indeed, EZM2302, a CARM1-specific inhibitor, inhibits CARM1-mediated GATAD2A methylation, GATAD2A chromatin binding, transcriptional activation of cell cycle genes, cell cycle progression, and eventually tumor growth." (PMID 38676947, 2024). "Finally, a potential role for SLC25A39 and GATAD2A in tumor development in this patient is weakly supported by literature and the most likely candidate gene appears to be GLT8D1." (PMID 33963205, 2021). "The variations in GATAD2A (c.A65G),GLT8D1 (c.C955G) and SLC25A39 (c.C809T) were validated in all sequenced cases both in non-tumor and tumor samples, showing that these variations were constitutive mutations." (PMID 33963205, 2021). "These variations affected the following genes: AZIN1 (c.A1099G), COG3 (c.A1903G), COPA (c.A490G), GATAD2A (c.A65G), GLT8D1 (c.C955G) and SLC25A39 (c.C809T), and were all verified by Sanger sequencing on tumors and non-tumor DNA." (PMID 33963205, 2021). "We further tested the effect of CARM1 and GATAD2A on tumor growth in vivo by injecting nude mice subcutaneously with control MCF7 cells or cells infected with shRNA targeting CARM1 or GATAD2A, and then treated with estrogen to stimulate tumor growth." (PMID 38676947, 2024). "Third, no fusion transcript shared by all tumors was found and only variations in three genes were detected both in tumor and non-tumor tissues: SLC25A39 (c.C809T),GLT8D1 (c.C955G) and GATAD2A (c.A65G)." (PMID 33963205, 2021). "The in vivo tumor formation assay suggested that hsa_circ_0058124 knockdown dramatically inhibited tumor growth when compared to the negative control group, whereas suppression of NOTCH3 or GATAD2A partly abolished this reduction of tumor growth by hsa_circ_0058124 knockdown." (PMID 31324198, 2019).
inflammation (1 paper, 2022). Aberrant reaction of the microcirculation characterized by movement of fluid and leukocytes from the blood into extravascular tissues. "SNPs in PNPLA3, TNF-α, AGTR1, IL-17A, IL-1B, PTPRD, and GATAD2A cause liver inflammation." (PMID 36000237, 2022).
GATAD2A also shares sentences with these, for which no sentence is quoted: fatty liver (2 papers); fatty liver disease (2); adolescent idiopathic scoliosis (1); bipolar disorder (1); eating disorder (1); Impaired glucose tolerance (1); liver fibrosis (1); major depressive disorder (1); mental disorder (1); prostate carcinoma (1); psychosis (1); type 2 diabetes (1).